PIK3CD (phosphatidylinositol-4,5-bisphosphate 3-kinase catalytic subunit delta)
Diseases named in the same sentence as PIK3CD in open-access papers (continued):
Sharing a sentence is not in itself a finding about the gene and the disease.
neuroblastoma (7 papers, 2011 to 2022). Neuroblastoma (NB) is the most common solid, extracranial childhood tumor. "Although a few mutations have been reported in PIK3CD, PIK3CD shows lower expression levels in aggressive neuroblastoma tumors compared to tumors with more favorable biology." (PMID 23597230, 2013). "In contrast, both mRNA and protein levels from PIK3CD/p110δ are decreased in stage 4 neuroblastoma compared to stage 1–2 as described by us and others previously." (PMID 23597230, 2013).
diabetes (6 papers, 2016 to 2024). "As a result, IRS-related signaling by IGF1R, which is directly related to diabetes, was derived (IRS2, IGF1R, PIK3CD, and PIK3CB)." (PMID 37608331, 2023). "PIK3CD and P2RY1 have not been reported in MI and atherosclerosis; however, Pik3cd is a critical gene in adipose-derived stem cells, which is the response to inflammation, which may be referred to in studies on diabetes." (PMID 34925642, 2021).
pancreatic cancer (6 papers, 2013 to 2025). "Mechanistic insights link its activity to Rac1 stimulation, Rho attenuation, and PIK3CD amplification, with further implications in tumor–stroma interplay impacting pancreatic cancer resilience and expansion." (PMID 39624211, 2024). "Suppression of PIK3CD in Tregs protected host mice from a broad range of transplanted cancers, but it is unclear if downregulation of PIK3CD slowed pancreatic cancer growth in vivo." (PMID 31112530, 2019). "PRKCZ has been shown to correlate with metastasis potential in pancreatic cancer cells, and PLCG1 and PIK3CD have been demonstrated to be associated with invasiveness of several cancer cells." (PMID 23451142, 2013). "However, we note expression of the strongly Arg1-correlated gene, PIK3CD, in macrophage populations in human pancreatic tumors." (PMID 35156921, 2022). "Signaling by PIK3CG and PIK3CD in leukocytes, but not in tumor cells, can affect how the immune system responds to tumors in murine models, including pancreatic cancer." (PMID 31112530, 2019).
respiratory infections (6 papers, 2014 to 2023). "In this study, the patient with the PIK3CD c.3061G > A mutation was an 8-year-old boy who had a history of multiple respiratory infections after birth." (PMID 34112210, 2021). "In the first report of gain-of-function PIK3CD mutations, patients were screened for frequent respiratory infections and family histories of increased susceptibility to infection; accordingly, all 17 had recurrent upper or lower respiratory tract infections." (PMID 29599765, 2018).
Insulin resistance (5 papers, 2020 to 2025). Increased resistance towards insulin, that is, diminished effectiveness of insulin in reducing blood glucose levels. "Estradiol levels were lower andglucose blood levels and insulin resistance were higher in Sham operated (Sham) males compared to Sham females.Irs2, Pik3cd, and Esr1/2 mRNA levels were lower in the liver of Sham males than in Sham females." (PMID 33659826, 2020).
common variable immunodeficiency (4 papers, 2020 to 2025). "Previously, studies have found an increase in CD21lo B cells in common variable immunodeficiency (CVID) patients, including patients with PIK3CD gene mutation." (PMID 38634985, 2024). "Similarly, activated PI3Kδ syndrome (APDS), due to PIK3CD or PIK3R1 mutations, and common variable immunodeficiency (CVID) have been associated with EBV-positive lymphomas, reflecting impaired immune regulation and defective viral clearance." (PMID 41367858, 2025).
COVID-19 (4 papers, 2021 to 2023). A disease caused by infection with severe acute respiratory syndrome coronavirus 2. "And the key targets of these important pathways, such as AKT1, PIK3CA, PIK3CD and CEP, all have good binding energy, which reveals that CEP treats COVID-19 mainly by acting on these key targets and regulating related pathways." (PMID 35935817, 2022). "Other genes that have been annotated in public database KEGG for their role in the COVID-19 pathway include NLRP3 (NLR family pyrin domain containing 3), MAPK10 (mitogen-activated protein kinase 10), and PIK3CD (phosphatidylinositol-4,5-bisphosphate 3-kinase catalytic subunit delta)." (PMID 36800980, 2023). "In addition, VEGF signaling pathway and HIF-1 signaling pathway are also rich in key targets such as AKT1, PIK3CA and PIK3CD, which may be related to the effect of CEP on COVID-19." (PMID 35935817, 2022).
gastric cancer (4 papers, 2018 to 2024). A primary or metastatic malignant neoplasm involving the stomach. "The molecular mechanism diagram of contribution of PIK3CD in gastric cancer development." (PMID 38545256, 2024).
non-small cell lung carcinoma (4 papers, 2012 to 2021). A group of at least three distinct histological types of lung cancer, including non-small cell squamous cell carcinoma, adenocarcinoma, and large cell carcinoma. "CDR1as acts as miR-7 sponges to upregulate targets of miR-7 including EGFR, CCNE1, and PIK3CD in non-small-cell lung cancer." (PMID 34221006, 2021). "Zhang reached a similar conclusion using non-small-cell lung cancer (NSCLC) and found that CDR1as functions as an oncogene that inhibits the anti-tumor effects of miR-7 by upregulation of the proliferation indices Ki-67, EGFR, CCNE1, and PIK3CD." (PMID 32765960, 2020).
SHORT syndrome (4 papers, 2021 to 2025). A rare disorder characterized by multiple congenital anomalies, including short stature, hyperextensibility of joints, ocular depression, Rieger anomaly and teething delay in which the cause of the disease is a mutation in PIK3R1 gene. "Four patients with APDS1 and confirmed variants in PIK3CD (P1, P2, P5 and P6) and 3 patients with APDS2 and SHORT syndrome harboring variants in PI3KR1 (P3, P4 and P7) were included." (PMID 39620215, 2024). "Biochemical studies demonstrate that differences between SHORT syndrome and APDS2 are attributable to different profiles of activation or repression of PIK3CA and PIK3CD by mutant PIK3R1 products." (PMID 34040190, 2021).
T-cell lymphoma (4 papers, 2018 to 2025). "Missense mutations in STAT5B, STAT3, and PIK3CD have also been reported and, similar to other T-Cell lymphomas, also occur in the SRC homology 2 domains, causing constitutive activation of the proteins." (PMID 35330161, 2022). "In contrast, mutations in PIK3CD and CREBBP were associated with inferior outcomes in T-cell lymphomas, highlighting the immunophenotype-specific impact of genetic alterations on treatment responses." (PMID 40506464, 2025). "Considering the B- and T-cell lymphoma cell lines exposed to both PI3K inhibitors (n = 41), the correlation between AUC values and PIK3CD mRNA expression was stronger for IOA-244 (R2 = 0.19, P = 0.005), than for idelalisib (R2 = 0.11, P = 0.033)." (PMID 37066023, 2023).
inflammatory bowel disease (3 papers, 2018 to 2023). A spectrum of small and large bowel inflammatory diseases of unknown etiology. "Also, a patient with biallelic loss-of-function mutations in the PIK3CD gene and reduced p110δ expression was reported to have B lymphopenia and hypogammaglobulinemia, sinopulmonary infections, septic arthritis, inflammatory bowel disease, and autoimmune hepatitis." (PMID 29535736, 2018).
laryngeal squamous cell carcinoma (3 papers, 2020 to 2023). A squamous cell carcinoma that arises from the larynx. "In laryngeal squamous cell carcinoma, the miR-30c-5p/PIK3CD axis is related to malignant properties and predicts a prognosis." (PMID 37861728, 2023). "In individuals with laryngeal squamous cell carcinoma, PIK3CD expression was elevated and could predict a bad prognosis." (PMID 37861728, 2023).
type 2 diabetes (3 papers, 2021 to 2025). "PAK3, CD44, CD5, SOCS3, VAV1, and PIK3CD are negatively correlated with cardiac systolic function, and P2RY1 is positively correlated with LVEF, which may be referred to in studies on type 2 diabetes." (PMID 34925642, 2021).
Virus Infections (3 papers, 2015 to 2022). "Mutations at seven sites in PIK3CD—E81K, G124D, N334K, C416R, E525K, E1021K, and E1025G—have been reported in persons with herpesvirus viremia or severe virus infections." (PMID 29599765, 2018). "CD4 T cell numbers were reduced in 72% of patients, and CD8 T cell and NK cell numbers were reduced in 27% of patients with severe virus infections and PIK3CD mutations." (PMID 29599765, 2018). "PIK3CD is a well-studied immune gene that not only shape the development and function of B cells, but also is responsible for the susceptibility of T cells to virus infection." (PMID 35767190, 2022). "Viral infections in patients with germline gain-of-function mutations in PIK3CD." (PMID 29599765, 2018). "Activated PI3Kδ syndrome patients that harbor activating mutations in the gene that encodes p110δ (PIK3CD) suffer from recurrent bacterial and viral infections." (PMID 26311905, 2015).
X-linked agammaglobulinemia (3 papers, 2021 to 2025). X-linked agammaglobulinemia (XLA) is a clinically variable form of isolated agammaglobulinemia, an inherited immunodeficiency disorder (see this term), and is characterized in affected males by recurrent bacterial infections during infancy. "SCID, CIDs, DiGeorge syndrome, Wiskott-Aldrich syndrome, Ataxia telangiectasia, Dyskeratosis congenita, ORAI-1 deficiency, CGD, X-linked Agammaglobulinemia, ALPS, STAT1 gain of function, CTLA-4 deficiency, GATA-2 deficiency, TRAPS, FMF, NEMO, TIM3, DOCK8, STAT2, STAT3, PIK3CD." (PMID 41049857, 2025).
acute megakaryocytic leukaemia (2 papers, 2018 to 2019). "The Runx1 target, Pik3cd, is a member of the mTOR pathway and directly regulated by Runx1 in acute megakaryocytic leukaemia cells." (PMID 31395869, 2019).
chronic granulomatous disease (2 papers, 2022). Chronic granulomatous disease (CGD) is a rare primary immunodeficiency, mainly affecting phagocytes, which is characterized by an increased susceptibility to severe and recurrent bacterial and fungal infections, along with the development of granulomas. "Genetic defects in PNP, PIK3CD, STAT1, ISG15, IL2RB, GS3, DNASE2 and genes associating chronic granulomatous disease were found among 7 of the 25 patients who underwent genetical testing." (PMID 35964089, 2022).
combined immunodeficiency (2 papers, 2017 to 2018). A broad classification of inherited disorders presenting at birth that affect both the cell-mediated and humoral aspects of the immune response. "Activated phosphoinositide 3-kinase δ syndrome (APDS) is a recently described combined immunodeficiency resulting from gain-of-function mutations in PIK3CD, the gene encoding the catalytic subunit of phosphoinositide 3-kinase δ (PI3Kδ)." (PMID 27555459, 2017).
endometrial cancer (2 papers, 2024 to 2025). Primary or metastatic malignant neoplasm involving the endometrium (mucous membrane that lines the endometrial cavity). "Consequently, mutation rates for PIK3CA are at least 10-fold higher than PIK3CB/PIK3CD/PIK3CG in solid tumours such as breast and endometrial cancer (TCGA Research Network)." (PMID 40360883, 2025).
epilepsy (2 papers, 2015 to 2022). A brain disorder characterized by episodes of abnormally increased neuronal discharge resulting in transient episodes of sensory or motor neurological dysfunction, or psychic dysfunction. "Within the network, many genes are related to inflammation and apoptosis, such as MAPK1, ATM, MYD88, RBL1, TRAF6, PIK3CD, IFNAR2, etc, indicating that these miRNAs may play a role in drug-resistant epilepsy through inflammation and apoptosis." (PMID 25984652, 2015).
Hypertension (2 papers, 2016 to 2021). The presence of chronic increased pressure in the systemic arterial system. "Similarly, the pathway-based 2-locus epistasis analysis indicated significant interactions between INSR and PRKCG for SBP and MAP; INS and PIK3R2 for DBP; PIK3CD and ATP1B2 for hypertension in the real data set." (PMID 27980660, 2016).
Intellectual disability (2 papers, 2020 to 2025). "In contrast, in females, DAS gene networks, including Ubap2l, Pik3cd, and Meis2, were primarily associated with neuritogenesis, neuronal development, and intellectual disability." (PMID 40790242, 2025).
lung carcinoma (2 papers, 2019 to 2021). "Besides, circCDR1as, one of the most frequently studied circRNAs, targets miR-7 in a manner dependent on NF-kB regulatory signaling, upregulates proliferation levels of EGFR, CCNE1, and PIK3CD, and thus induced superior proliferative, migratory, and invasive capabilities of lung cancer cells." (PMID 31534962, 2019). "Furthermore, we found increased mRNA of PIK3CB, PIK3CD, PIK3CG, BCL2, TUBB3 in ALK-positive lung cancer, which suggested activation of PI3K/AKT signaling pathway." (PMID 34234236, 2021).
mantle cell lymphoma (2 papers, 2014 to 2021). Mantle cell lymphoma is a rare form of malignant non-Hodgkin lymphoma affecting B lymphocytes in the lymph nodes in a region called the ``mantle zone''. "Furthermore, in mantle cell lymphoma, it was shown in vitro that a higher PIK3CA (encoding for p110α)/PIK3CD (encoding for p110δ) ratio of messenger RNA transcripts is associated to PI3Kδi resistance." (PMID 34959482, 2021).
medulloblastoma (2 papers, 2013 to 2015). A malignant, invasive embryonal neoplasm arising from the cerebellum. "This hypothesis was also confirmed by the observation that PIK3CA was over-expressed in primary medulloblastoma, compared to normal cerebellum, which was not the case for PIK3CB or PIK3CD." (PMID 25915540, 2015).
osteosarcoma (2 papers, 2022). A usually aggressive malignant bone-forming mesenchymal neoplasm, predominantly affecting adolescents and young adults. "The results showed that the low expression of PIK3CD was associated with poor overall survival and metastasis free survival in patients with osteosarcoma." (PMID 35651811, 2022).
seminoma (2 papers, 2018 to 2021). A radiosensitive malignant germ cell tumor found in the testis (especially undescended), and extragonadal sites (anterior mediastinum and pineal gland). "All mutations in these genes of interest were in seminomas, except for one PIK3CD mutation found in a non-seminoma." (PMID 34819066, 2021).
vascular malformation (2 papers, 2024 to 2025). A non-neoplastic disorder that is the result of defects of vascular morphogenesis. "The remaining four genes (ARAF, CBL, GNB2 and PIK3CD) have been associated with vascular malformations with “limited evidence”." (PMID 38778413, 2024).
acute promyelocytic leukemia (1 paper, 2020). An aggressive form of acute myeloid leukemia (AML), characterized by arrest of leukocyte differentiation at the promyelocyte stage, due to a specific chromosomal translocation t(15;17) in myeloid cells. "Phosphoinositide-3-kinase catalytic delta polypeptide (PIK3CD) shows anti-apoptotic effects on all-trans-retinoic acid in acute promyelocytic leukemia cells and is downregulated in BDH2-KD THP1 cells." (PMID 32344823, 2020).
anaplastic thyroid cancer (1 paper, 2023). "MiR-125b may exert its tumor suppressor function by directly interacting with the delta-catalytic subunit of phosphoinositide 3-kinase (PIK3CD) and reducing its expression, as shown in the anaplastic thyroid cancer cell line (ATC)." (PMID 37443682, 2023).
Cerebral ischemia (1 paper, 2025). Restriction of arterial blood supply to the brain associated with insufficient oxygenation to support the metabolic requirements of the tissue. "Furthermore, it has recently been shown that the inhibition of PI3Kδ which is encoded by the Pik3cd gene alleviates brain injury during cerebral ischemia–reperfusion via suppressing pericyte contraction in a TNF-α-dependent manner." (PMID 40076966, 2025).
cognitive decline (1 paper, 2025). "Causative or predisposing variants have been linked to altered PI3K signaling with increased risk of cognitive decline in PIK3CD, AKT3, and TSC1/2." (PMID 40806341, 2025).
Cognitive impairment (1 paper, 2019). Abnormal cognition is characterized by deficits in thinking, reasoning, or remembering. "Among the significantly enriched signaling pathways from KEGG analysis, oxytocin signaling pathway (PATH:04921; Cacng2, Adcy1, Kcnj4, Kcnj9, Adcy8, Pik3cd, Elk1, Adcy4, Camkk2, Cacng7, Nos3, Kcnj2) may play an important role in the sevoflurane-induced cognitive impairment." (PMID 31582589, 2019).
cutaneous T-cell lymphoma (1 paper, 2013). "And increased expression of PIK3CD gene (encoding PI3K δ isoform), was found in peripheral and cutaneous T-cell lymphoma." (PMID 24252186, 2013).
diabetic retinopathy (1 paper, 2024). "Similarly, PIK3CD plays a significant role in diabetic retinopathy, with high glucose levels upregulating its expression and promoting retinal angiogenesis, while its inhibition suppresses pathological angiogenesis." (PMID 38904047, 2024).
Epstein-Barr virus infection (1 paper, 2024). An infection that is caused by Epstein-Barr virus. "Concurrent deficiencies in PIK3CD and TNFRSF9 result in chronic active Epstein-Barr virus infections in T cells." (PMID 39845086, 2024).
hearing loss (1 paper, 2022). "The genes Elane, Pik3cd, and Il4r have also been previously associated with noise-induced and age-related hearing loss." (PMID 35454087, 2022).
Herpesvirus Infections (1 paper, 2018). "In the largest review to date, a total of 53 patients with PIK3CD gain-of-function mutations were reported, and 49% had persistent or recurrent herpesvirus infections." (PMID 29599765, 2018). "Since these two reports were published, additional papers have reported persistent herpesvirus viremia or severe herpesvirus infections in patients with PIK3CD gain-of-function mutations." (PMID 29599765, 2018).
intracranial aneurysms (1 paper, 2025). "The human genome has been demonstrated to encode three classes of intracranial aneurysms (IA) p110 isoforms, including p110α (encoded by PIK3CA) and p110β (PIK3CB), demonstrating expression in various cell types, and p110δ (PIK3CD), with specific expression in immune cells." (PMID 40740483, 2025).
laryngeal carcinoma (1 paper, 2021). Carcinoma that arises from the laryngeal epithelium. "Additionally, in laryngeal cancer, DLEU2 enhances the malignant properties of the cancer cells via the miR-30c-5p/PIK3CD/Akt axis." (PMID 34572265, 2021).
lymph node metastasis (1 paper, 2020). "Moreover, the LSCC patients with an advanced tumor stage, the presence of lymph node metastasis and a higher TNM stage showed increased PIK3CD expression, compared to the matched group of controls." (PMID 32555190, 2020).
mesothelioma (1 paper, 2020). A usually malignant and aggressive neoplasm of the mesothelium which is often associated with exposure to asbestos. "Both PI3K genes, PIK3CA and PIK3CD, all 3 AKT genes, AKT1, AKT2 and AKT3, as well as BCL2 gene were detected in mesothelium and mesothelioma samples." (PMID 32664372, 2020).
migraine (1 paper, 2022). "PIK3CA, PIK3CB, and PIK3CD are important genes involved in cell proliferation, G protein-coupled receptor signal transduction, and cancer gene expression, and they may be related to migraine caused by glial neuron tumors." (PMID 36479181, 2022).
Neurodevelopmental delay (1 paper, 2021). "A subset of APDS patients also displays neurodevelopmental delay symptoms, suggesting a potential role of PIK3CD in cognitive and behavioural function." (PMID 34786564, 2021).
oral squamous cell carcinoma (1 paper, 2025). "For example, in oral squamous cell carcinoma (OSCC), circ_CDR1as can act as a sponge for miR-7, leading to the attenuation of the miR-7 targets RAF-1 and PIK3CD, which promotes metastatic progression of tumors by regulating the MAPK/AKT signaling pathway." (PMID 40657383, 2025).
Parkinson disease (1 paper, 2025). A progressive degenerative disorder of the central nervous system characterized by loss of dopamine producing neurons in the substantia nigra and the presence of Lewy bodies in the substantia nigra and locus coeruleus. "For instance, the genes PIK3CD and PIK3C3 that code for the PI3K isoform are linked to higher chances of AD and Parkinson’s disease, respectively." (PMID 40806341, 2025).